OR6K3 (olfactory receptor family 6 subfamily K member 3)
Description:
Odorant receptor.
Synonyms: OR1-18
Tractability: Antibody: UniProt places it where antibodies can reach, with medium confidence; UniProt predicts a signal peptide or a membrane-spanning region; its Gene Ontology location is reachable by antibodies, with medium confidence.
Gene: Protein-coding gene on chromosome 1 (158,716,327 to 158,720,720, reverse strand). Ensembl gene ENSG00000203757.
Subcellular location: Cell membrane
Pathways (Reactome):
Sensory Perception: Expression and translocation of olfactory receptors
Gene Ontology:
Molecular function: odorant binding; olfactory receptor activity; G protein-coupled receptor activity
Biological process: detection of chemical stimulus involved in sensory perception of smell; G protein-coupled receptor signaling pathway
Cellular component: membrane; plasma membrane
Genetic constraint (gnomAD): Missense variants: 389 observed, 395.27 expected, observed/expected ratio (o/e) 0.98, 90% interval 0.9 to 1.07. Synonymous variants: 166 observed, 142.15 expected, observed/expected ratio (o/e) 1.17, 90% interval 1.03 to 1.33.
Homologues: Orthologues: chimpanzee OR6K3 (97% identical), macaque OR6K3 (96% identical), dog OR6K3 (83% identical), rabbit OR6K3 (77% identical), mouse Or6k4 (77% identical), pig OR6K3 (76% identical), rat Or6k4 (76% identical), guinea pig OR6K3 (62% identical). Paralogues in human: OR6K6 (63% identical), OR6K2 (60% identical), OR6N1 (52% identical), OR6N2 (52% identical), OR10Z1 (42% identical), OR1L6 (42% identical), OR1L1 (42% identical), OR1L8 (41% identical), OR1L3 (41% identical), OR1L4 (41% identical), OR1S1 (41% identical), OR10K1 (41% identical), and 116 more.